PSMD3 (proteasome 26S subunit, non-ATPase 3)
Description:
Component of the 26S proteasome, a multiprotein complex involved in the ATP-dependent degradation of ubiquitinated proteins. This complex plays a key role in the maintenance of protein homeostasis by removing misfolded or damaged proteins, which could impair cellular functions, and by removing proteins whose functions are no longer required. Therefore, the proteasome participates in numerous cellular processes, including cell cycle progression, apoptosis, or DNA damage repair.
Synonyms: S3; P58; Rpn3; TSTA2
Tractability: Small molecule: an approved drug acts on it; a structure with a bound ligand is known; a high-quality ligand is known. Antibody: its Gene Ontology location is reachable by antibodies, with high confidence. PROTAC: UniProt records ubiquitination sites on it; ubiquitination databases record sites on it; its protein half-life has been measured.
Target class: Enzyme
Gene: Protein-coding gene on chromosome 17 (39,980,800 to 39,997,960, forward strand). Ensembl gene ENSG00000108344.
Subcellular location (Human Protein Atlas): Nucleoplasm; Cytosol
Pathways (Reactome):
Immune System: AMPK-induced ERAD and lysosome mediated degradation of PD-L1(CD274); Activation of NF-kappaB in B cells; Antigen processing: Ubiquitination & Proteasome degradation; CLEC7A (Dectin-1) signaling; Cross-presentation of soluble exogenous antigens (endosomes); Dectin-1 mediated noncanonical NF-kB signaling; Downstream TCR signaling; ER-Phagosome pathway; FCERI mediated NF-kB activation; GSK3B-mediated proteasomal degradation of PD-L1(CD274); Interleukin-1 signaling; NIK-->noncanonical NF-kB signaling; Neutrophil degranulation; SPOP-mediated proteasomal degradation of PD-L1(CD274); TNFR2 non-canonical NF-kB pathway
Cell Cycle: APC/C:Cdc20 mediated degradation of Securin; APC/C:Cdh1 mediated degradation of Cdc20 and other APC/C:Cdh1 targeted proteins in late mitosis/early G1; Autodegradation of Cdh1 by Cdh1:APC/C; Autodegradation of the E3 ubiquitin ligase COP1; Cdc20:Phospho-APC/C mediated degradation of Cyclin A; FBXL7 down-regulates AURKA during mitotic entry and in early mitosis; G2/M Checkpoints; SCF(Skp2)-mediated degradation of p27/p21; SCF-beta-TrCP mediated degradation of Emi1; Separation of Sister Chromatids; The role of GTSE1 in G2/M progression after G2 checkpoint; Ubiquitin-Mediated Degradation of Phosphorylated Cdc25A; Ubiquitin-dependent degradation of Cyclin D
Signal Transduction: Asymmetric localization of PCP proteins; Degradation of AXIN; Degradation of DVL; Degradation of GLI1 by the proteasome; Degradation of GLI2 by the proteasome; Degradation of beta-catenin by the destruction complex; GLI3 is processed to GLI3R by the proteasome; Hedgehog 'on' state; Hedgehog ligand biogenesis; MAPK6/MAPK4 signaling; Negative regulation of NOTCH4 signaling; Regulation of PTEN stability and activity
and 28 more pathways
Gene Ontology:
Molecular function: protein binding; enzyme regulator activity
Biological process: cellular response to type I interferon; proteasomal protein catabolic process; proteasome-mediated ubiquitin-dependent protein catabolic process; regulation of proteasomal protein catabolic process; response to oxidative stress; ubiquitin-dependent protein catabolic process; regulation of protein catabolic process
Cellular component: cytosol; extracellular exosome; membrane; nucleoplasm; nucleus; proteasome complex; extracellular region; ficolin-1-rich granule lumen; proteasome accessory complex; proteasome regulatory particle, lid subcomplex; secretory granule lumen; synaptic vesicle; proteasome regulatory particle
Genetic constraint (gnomAD): Loss-of-function variants: 5 observed, 61.57 expected, observed/expected ratio (o/e) 0.0812, 90% interval 0.041 to 0.17. The upper end of that interval is the gene's LOEUF score, 0.17, which puts it in group 1 of 6, group 1 being the genes least tolerant of losing a copy. Missense variants: 524 observed, 713.05 expected, observed/expected ratio (o/e) 0.73, 90% interval 0.68 to 0.79. Synonymous variants: 265 observed, 285.55 expected, observed/expected ratio (o/e) 0.93, 90% interval 0.84 to 1.03.
Homologues: Orthologues: chimpanzee PSMD3 (99% identical), macaque PSMD3 (99% identical), dog PSMD3 (98% identical), pig PSMD3 (98% identical), mouse Psmd3 (97% identical), guinea pig PSMD3 (97% identical), rat Psmd3 (97% identical), tropical clawed frog psmd3 (83% identical), zebrafish psmd3 (81% identical), rabbit PSMD3 (77% identical), Drosophila melanogaster Rpn3 (54% identical), Caenorhabditis elegans rpn-3 (42% identical). Paralogues in human: COPS3 (19% identical).
Diseases named in the same sentence as PSMD3 in open-access papers:
PSMD3 is named in the same sentence as 50 diseases in open-access papers, as found by Europe PMC text mining. Sharing a sentence is not in itself a finding about the gene and the disease. The quoted sentences say what the papers report.
breast carcinoma (17 papers, 2010 to 2026). "As for RS hub genes, high PSMD3 expression was associated with poor prognosis in the breast cancer patients." (PMID 34212001, 2021). "Significantly, PSMD3 is highly expressed in malignant and metastatic breast cancers, particularly triple-negative breast cancer." (PMID 41633985, 2026). "Knockdown of PSMD3 led to reduced cell proliferation, reduced colony formation, and increased apoptosis in breast cancer cell lines, and co-silencing of PSMD3 and HER2 resulted in additive inhibition of cell viability and promoted apoptosis in breast cancer." (PMID 34572038, 2021). "Consistently, PSMD3 is upregulated in breast cancer compared with normal tissue, and patients with a higher expression level of PSMD3 are related with worse survival." (PMID 34804978, 2021). "Silencing of PSMD3 has been shown to have an additive inhibition of cell viability as well as induced apoptosis in HER2+ breast cancer cells." (PMID 30404658, 2018). "PSMD3 controls breast cancer through the stabilization of HER2 from degradation." (PMID 37337223, 2023). "PSMD3 regulates breast cancer by stabilizing HER2 degradation." (PMID 37349676, 2023). "The increased expression of PSMD3 was also related to poor prognosis for breast cancer patients." (PMID 37337223, 2023). "Moreover, the expression of PSMD3 was significantly higher in breast cancer tissue compared to normal tissues." (PMID 37337223, 2023). "However, mutation events in PSM genes were relatively rare in cancer, which was also observed in the breast cancer validation dataset where only four PSM genes (PSMA4, PSMB7, PSMD3, and PSME4) harbored mutations." (PMID 36123629, 2022). "Similarly, PSMD3 was shown to be overexpressed at the protein level in human epidermal growth factor receptor 2 (HER2)-positive breast cancer, helping to stabilize HER2 and culminating in a worse overall survival (OS)." (PMID 34572038, 2021). "The levels of PSMD1, PSMD2, PSMD3, PSMD7, PSMD10, PSMD12, and PSMD14 are high in breast cancer tissue compared to normal tissues." (PMID 36934426, 2023). "At the protein level, PSMD3 was found to be upregulated in 5/5 (100%) CPTAC cancers, including breast cancer, colon cancer, ovarian cancer, clear cell RCC, and UCEC." (PMID 34572038, 2021). "Cluster 2 (dark-blue) consisted of genes that are up-regulated in HER2+ breast cancer, including ERBB2, GRB7, STARD3 and PSMD3 that are located in the HER2 amplicon." (PMID 23945349, 2013). "In addition, the genes TCAP, PSMD3, GRB7, and ERBB2 from the ERBB2 group are derived from the same well known breast cancer amplicon." (PMID 20158879, 2010).
chronic myeloid leukemia (8 papers, 2021 to 2024). "PSMD3 exerts an oncogenic effect on chronic myeloid leukemia (CML) by stabilizing of nuclear factor-kappa B, therefore, PSMD3 is considered as a potential target for anti-cancer therapeutics in CML." (PMID 37337223, 2023). "PSMD3 promotes nuclear factor kappa-light-chain-enhancer of activated B cells protein expression in chronic myeloid leukemia cells and, thus, promotes disease progression to a chronic state." (PMID 34445011, 2021). "Besides this, the higher level of PSMD3 mRNA predicts a worse prognosis of acute myeloid leukemia patients, and PSMD3 promotes the progression of chronic myeloid leukemia by stabilizing NF-kB." (PMID 34804978, 2021). "PSMD3 promoted NF-κB protein expression and was upregulated in TKI-resistant chronic myeloid leukemia (CML) cells." (PMID 34610582, 2021). "26S proteasome non-ATPase subunits 1 (PSMD1) and 3 (PSMD3) were recently identified as prognostic biomarkers and potential therapeutic targets in chronic myeloid leukemia (CML) and multiple solid tumors." (PMID 36498916, 2022). "We previously reported a role for two members of the 19S regulatory complex, 26S proteasome non-ATPase subunits 1 (PSMD1) and 3 (PSMD3), in disease progression and drug resistance of chronic myeloid leukemia (CML) and several types of solid tumors." (PMID 36498916, 2022). "We recently demonstrated that two members of the 19S regulatory complex, 26S proteasome non-ATPase subunits 1 (PSMD1) and 3 (PSMD3), may be potential targets for therapy in tyrosine kinase inhibitor (TKI)-resistant chronic myeloid leukemia (CML) cells." (PMID 34572038, 2021).
acute myeloid leukemia (5 papers, 2021 to 2025). Acute myeloid leukemia (AML) is a group of neoplasms arising from precursor cells committed to the myeloid cell-line differentiation. "In acute myeloid leukemia, patients with high level of PSMD3 mRNA have a poor prognosis." (PMID 34610582, 2021). "In acute myeloid leukemia (AML), patients with higher levels of PSMD3 mRNA were shown to have a worse overall survival than patients with lower levels of expression." (PMID 33712704, 2021). "CDK12 is an oncogene which is up-regulated and has highest expression level in Acute Myeloid Leukemia (AML), while its partner boundary non-oncogene PSMD3 shows down-regulation in AML patients." (PMID 38105946, 2023). "CDK12 is an oncogene, which is up-regulated and has the highest expression level in Acute Myeloid Leukemia (AML), while its boundary partner non-oncogene PSMD3 shows down-regulation in AML patients." (PMID 40051047, 2025).
Insulin resistance (4 papers, 2018 to 2025). Increased resistance towards insulin, that is, diminished effectiveness of insulin in reducing blood glucose levels. "However, other PSMD3 SNPs have been linked to insulin resistance in different populations, with evidence suggesting that these associations may be modulated by dietary factors." (PMID 41441015, 2025). "Similarly, the rs4065321 and rs709592 SNPs in the PSMD3 (RPN3) were associated with glucose-related traits and insulin resistance, with evidence suggesting that these associations may be modulated by dietary factors." (PMID 41441015, 2025). "Of these, PSMD3 is an enzyme, an aberration of which contributes to pathogenesis of neurodevelopmental and neurodegenerative disorders and insulin resistance." (PMID 31455857, 2020). "Rosiglitazone targeted 613 genes, among them, PSMD3 is involved in regulating insulin signaling to mediate insulin resistance." (PMID 30521536, 2018). "We combined this hub gene analysis with GWAS association gene scores, and observed that PSMB5, UBE2L3, and PSMD3 are important in many age-related diseases or phenotypes, such as Alzheimer’s disease, HDL cholesterol, LDL cholesterol, triglycerides, and insulin resistance." (PMID 31269015, 2019).
colon cancer (2 papers, 2017 to 2021). "Knock-down of PSMA3 (20S proteasomal protein), PSMD3 (19S proteasomal protein), and PSME1 (11S proteasomal protein) resulted in increased size and quantity of FoxM1 compared with control colon cancer cells (brace)." (PMID 28378765, 2017).
glioma (2 papers, 2020 to 2021). A benign or malignant brain and spinal cord tumor that arises from glial cells (astrocytes, oligodendrocytes, ependymal cells). "Moreover, the results of the Kaplan–Meier analysis indicated that PSMD3 was significantly associated with worse overall survival of the glioma patients (P < 0.05)." (PMID 34804978, 2021). "Consistently, we found that the expression level of PSMD3 was positive with the grade of glioma." (PMID 34804978, 2021). "In addition, a high risk score hinted an immunosuppressive microenvironment and lower sensitivity of ICB therapy, and PSMC5 and PSMD3 were identified as novel biomarkers in glioma." (PMID 34804978, 2021). "Furthermore, the high risk score hinted an immunosuppressive microenvironment and a lower sensitivity of immune checkpoint blockade therapy and also identified PSMC5 and PSMD3 as novel biomarkers in glioma." (PMID 34804978, 2021). "Besides this, we also have identified PSMC5 and PSMD3 as new biomarkers in glioma." (PMID 34804978, 2021). "All the results confirmed that PSMD3 and PSMC5 can be identified as potential biomarkers in glioma patients." (PMID 34804978, 2021).
lung adenocarcinoma (2 papers, 2020 to 2021). A carcinoma that arises from the lung and is characterized by the presence of malignant glandular epithelial cells. "Seven other 26S/20S proteasome subunits were isolated (q < 0.05; PSMD12, PSMB4, PSMA6, PSMB6, PSMC1, PSMD3, and PSMB3), illuminating the importance of the 26/20S proteasome integrity in lung adenocarcinoma genome maintenance." (PMID 34070461, 2021).
pancreatic cancer (2 papers, 2020 to 2025). "Systematic evaluation of PSMD1-14 expression revealed significant upregulation (p<0.05) of PSMD1, PSMD2, PSMD3, PSMD4, PSMD7-PSMD14 transcripts in pancreatic tumor tissues compared with adjacent normal controls, with the notable exception of PSMD6 which demonstrated reduced mRNA expression." (PMID 40182048, 2025).
breast tumor (1 paper, 2021). "Immunohistochemical (IHC) images revealed dense distributions of PSMD2 and PSMD4, while the other PSMDs, including PSMD1, PSMD2, PSMD3, PSMD7, PSMD12, and PSMD14, were moderately distributed in breast tumor samples." (PMID 34839279, 2021).
coronary artery disease (1 paper, 2019). "Although only the PSMB5 gene was an experimentally validated candidate gene in mice, the PSMD3 gene was related with coronary artery disease, HDL cholesterol and fasting proinsulin, and would also be worthwhile to explore further." (PMID 31269015, 2019).
diabetes (1 paper, 2018). "PSMD3, a subunit of RNA polymerase, can induce the expression of Cox2, S100A4/FSP-1 and vimentin genes in renal, which contributes to diabetes-mediated chromatin turnover and promotes transcriptional changes in diabetic kidneys." (PMID 30521536, 2018).
diabetic kidney disease (1 paper, 2025). Progressive kidney disorder caused by vascular damage to the glomerular capillaries, in patients with diabetes mellitus. "The PSMA6 rs1048990G allele was linked to increased prevalence of diabetic kidney disease (DKD; OR = 1.75, 95% CI 1.02–2.99; p = 0.042), and the PSMD3 rs3087852A allele was associated with lower urinary albumin excretion." (PMID 41441015, 2025).
endothelial dysfunction (1 paper, 2025). In vascular diseases, endothelial dysfunction is a systemic pathological state of the endothelium (the inner lining of blood vessels) and can be broadly defined as an imbalance between vasodilating and vasoconstricting substances produced by (or acting on) the endothelium. "Moreover, the PSMD3 rs3087852 SNP has previously been associated with circulating levels of resistin, an adipokine secreted primarily by mononuclear cells that promotes pro-inflammatory responses and contributes to endothelial dysfunction." (PMID 41441015, 2025).
glioblastoma (1 paper, 2025). The most malignant astrocytic tumor (WHO grade IV). "We found loss of H3K27ac at genes related to Proteasome subunits type A, B, C and D (PSM), in particular PSMD1 and PSMD3, which have been shown to act as tumour suppressors and inhibit Wnt signalling in other cancers, though not yet described in glioblastoma." (PMID 39915814, 2025).
Hereditary breast cancer (1 paper, 2019). Breast carcinoma that has developed in relatives of patients with history of breast carcinoma. "Among the highest-scoring genes detected using the proposed method, it is suspected that STARD3, PGAP3, ORMDL3, PSMD3 and HAPLN3 are the biomarkers of the HER2 + subtype, thus indicating that FOXC1 can identify basal-like subtypes in hereditary breast cancer cohorts." (PMID 31296201, 2019).
ischemia (1 paper, 2022). A hypoperfusion of the BLOOD through an organ or tissue caused by a PATHOLOGIC CONSTRICTION or obstruction of its BLOOD VESSELS, or an absence of BLOOD CIRCULATION. "For example, miR-127-5p was found to have reduced expression in the brains of aged C57BL/6J mice undergoing LPS-induced ischemia, and for the first time, identified 26S proteasome non-ATPase regulatory subunit 3 (Psmd3) as one of its targets." (PMID 35328652, 2022).
ischemic stroke (1 paper, 2021). A stroke disorder caused by obstruction of blood flow to the brain, due to thrombotic (local blood clot formation) or embolic (due to a blood clot or other material traveling from another site) event. "To evaluate the expression levels of Psmd3 and PSMB5 in the peri‐ischemic samples, we carried out Western blotting to see whether their protein levels were altered in ischemic stroke in mice." (PMID 33369048, 2021).
lung carcinoma (1 paper, 2023). "The present study aims to research the role of PSMD3 in LC progression and explore the possible mechanisms involved in this regulation process, providing new targets for lung cancer therapy." (PMID 37337223, 2023). "Western blot analysis conformed the upregulation of PSMD3 at the protein level in tumor tissues by using 10 pairs of normal lung tissues (N) and lung cancer tissues (T)." (PMID 37337223, 2023). "This study observes the protein expression of PSMD3 markedly grew in lung cancer samples from TCGA database and clinical patients." (PMID 37337223, 2023). "Nevertheless, the function of PSMD3 in lung cancer (LC) remains unclear." (PMID 37337223, 2023). "We also determined that PSMD3 stabilized the protein expression of ILF3 and the deubiquitination of ILF3 in lung cancer cells." (PMID 37337223, 2023). "In conclusion, these findings suggested the interaction between PSMD3 and ILF3 in lung cancer cells." (PMID 37337223, 2023). "The interaction between PSMD3 and ILF3 in lung cancer cells were studied using IF staining, CHX protein stability, and ubiquitination assay." (PMID 37337223, 2023). "Additionally, our analyses revealed high expression of both PSMD3 and ILF3 among clinical patients with lung cancer." (PMID 37337223, 2023).
male infertility (1 paper, 2022). The inability of the male to effect fertilization of an ovum after a specified period of unprotected intercourse. "PSME3, PSMD3, and CDC27 were the top 3 hub genes identified within the male infertility network." (PMID 35918717, 2022).
multiple myeloma (1 paper, 2022). "Consistent with our findings, a previous study reported that PSMD1 or PSMD3 knockdown resulted in a greater reduction of growth in TKI-resistant multiple myeloma cells than in their TKI-sensitive counterparts." (PMID 36568232, 2022).
ovarian serous cystadenocarcinoma (1 paper, 2023). A malignant serous cystic epithelial neoplasm arising from the ovary. "The top five interacting genes were selected for analysis, and the results showed that PGAP3, GRB7, STARD3, and PSMD3 had a significant positive correlations with STAT3 in TCGA cancers, such as ovarian serous cystadenocarcinoma (OV)." (PMID 36977736, 2023).
thymoma (1 paper, 2021). A neoplasm arising from the epithelial cells of the thymus. "High levels of PSMD3 mRNA expression, in contrast, correlated with a worse OS in MESO and a better OS in thymoma (THYM)." (PMID 34572038, 2021).